ADGRF5 (adhesion G protein-coupled receptor F5)
Description:
Adhesion G protein-coupled receptor. In alveolar type II (ATII or AT2) cells, required for normal lung surfactant homeostasis. Modulation of both surfactant secretion and uptake by ATII cells is mediated by the downstream activation of GNAQ/GNA11 proteins and may be a consequence of increased cortical F-actin assembly induced by ADGRF5 activation. In the kidney, may play a role in the regulation of acid excretion into the primary urine, possibly by regulating the surface expression of V-ATPase proton pump (By similarity). As a receptor for soluble FNDC4 (sFNDC4), required for proper systemic glucose tolerance, specifically sensitizing white adipose tissue to insulin. Also plays a role in sFNDC4-induced decrease of local inflammation in white adipose tissue.
Synonyms: GPR116; KIAA0758; DKFZp564O1923; KPG_001
Tractability: Antibody: UniProt places it where antibodies can reach, with high confidence; UniProt predicts a signal peptide or a membrane-spanning region; its Gene Ontology location is reachable by antibodies, with medium confidence.
Target class: Family B G protein-coupled receptor; Membrane receptor
Gene: Protein-coding gene on chromosome 6 (46,852,310 to 46,956,392, reverse strand). Ensembl gene ENSG00000069122.
Subcellular location: Cell membrane
Pathways (Reactome):
Metabolism of proteins: Surfactant metabolism
Gene Ontology:
Molecular function: protein binding; G protein-coupled receptor activity; transmembrane signaling receptor activity
Biological process: adenylate cyclase-activating G protein-coupled receptor signaling pathway; energy reserve metabolic process; G protein-coupled receptor signaling pathway; glucose homeostasis; surfactant homeostasis; cell surface receptor signaling pathway
Cellular component: cell surface; cytoplasmic vesicle; plasma membrane; membrane; apical part of cell
Genetic constraint (gnomAD): Loss-of-function variants: 47 observed, 83.4 expected, observed/expected ratio (o/e) 0.56, 90% interval 0.44 to 0.72. The upper end of that interval is the gene's LOEUF score, 0.72, which puts it in group 2 of 6, group 1 being the genes least tolerant of losing a copy. Missense variants: 1,222 observed, 1,342.1 expected, observed/expected ratio (o/e) 0.91, 90% interval 0.87 to 0.95. Synonymous variants: 513 observed, 495.52 expected, observed/expected ratio (o/e) 1.04, 90% interval 0.96 to 1.11.
Homologues: Orthologues: chimpanzee ADGRF5 (99% identical), macaque ADGRF5 (95% identical), dog ADGRF5 (79% identical), rabbit ADGRF5 (78% identical), pig ADGRF5 (76% identical), rat Adgrf5 (73% identical), mouse Adgrf5 (72% identical), tropical clawed frog adgrf1 (37% identical). Paralogues in human: ADGRF1 (22% identical), ADGRF3 (19% identical), ADGRF4 (17% identical), ADGRG4 (16% identical), ADGRG6 (14% identical), ADGRL3 (13% identical), ADGRD1 (13% identical), ADGRL1 (13% identical), ADGRL2 (13% identical), ADGRB2 (13% identical), ADGRD2 (13% identical), ADGRB1 (13% identical), and 30 more.
Diseases named in the same sentence as ADGRF5 in open-access papers:
ADGRF5 is named in the same sentence as 57 diseases in open-access papers, as found by Europe PMC text mining. Sharing a sentence is not in itself a finding about the gene and the disease. The quoted sentences say what the papers report.
breast carcinoma (16 papers, 2015 to 2025). "More recent studies into the role of ADGRF5 in breast cancer metastasis showed that the loss of ADGRF5 in breast cancer cells reduced cell motility, extracellular matrix remodelling, and tumour growth." (PMID 39982274, 2025). "ADGRF5 (GPR116) has been identified as a facilitator of breast cancer cell migration and metastasis, yet the underlying mechanisms remain largely elusive." (PMID 38937435, 2024). "An increased ADGRF5 expression is associated with breast cancer progression and recurrence and poor prognosis of patients with breast cancer." (PMID 36497132, 2022). "However, modulating tier 1 protein of ADGRF5 was suggestively associated with an increased risk of ovarian cancer (p‐value of inverse variance‐weighted method = 0.047) and breast cancer (p‐value of inverse variance‐weighted method = 0.042)." (PMID 38898596, 2024). "In target safety assessments, MR analyses found that increased ADGRF5 levels were suggestively associated with an increased risk of ovarian cancer (p‐value of inverse variance‐weighted method = 0.047) and breast cancer (p‐value of inverse variance‐weighted method = 0.042)." (PMID 38898596, 2024). "The GPCR ADGRF5 has been shown to be a regulator of breast cancer metastasis, with knock out of ADGRF5 in triple negative breast cancer cells, reducing metastasis in mouse models." (PMID 39982274, 2025). "Overall, the data underscore ADGRF5 as a promising therapeutic target for breast cancer intervention." (PMID 38937435, 2024). "GPR116/ADGRF5 plays a critical role in promoting breast cancer progression and metastasis through the p63RhoGEF-RhoA/Rac1 signaling pathway." (PMID 36551877, 2022). "For example, increased expression levels of ADGRG1, ADGRE5, and ADGRF5 has been detected in a variety of human cancers such as glioma (ADGRG1), gastric, pancreatic, esophageal, prostate, colorectal carcinomas (ADGRE5), and breast cancer (ADGRF5)." (PMID 29468160, 2018). "Our current study reveals that the absence of ADGRF5 in breast cancer cells impairs extracellular matrix (ECM)-associated cell motility and impedes in vivo tumor growth." (PMID 38937435, 2024). "It should also be noted that the significance of ADGRF5 in breast cancer was evaluated in vitro and in vivo, and both approaches confirmed that ADGRF5 depletion in breast cancer cells was related to the reduced ability of breast cancer cells to migrate and invade." (PMID 36497132, 2022). "However, various aGPCRs have been associated with cancer development and progression including GPR133/ADGRD1, which is required for glioblastoma growth; GPR116/ADGRF5, which furthers breast cancer metastasis; and CD97/ADGRE5 seems to enhance tumor cell invasion in several human malignancies." (PMID 29594040, 2018). "ADGRF5 (GPR116), predicted to enable G protein-coupled receptor activity, has previously been shown to promote breast cancer metastasis." (PMID 36439479, 2022).
colorectal cancer (6 papers, 2017 to 2022). A primary or metastatic malignant neoplasm that affects the colon or rectum. "However, the significance of ADGRF5 expression signature and the impact of signaling pathways mediated by ADGRF5 during neoplastic transformation of the colon and colorectal cancer (CRC) progression has been poorly examined." (PMID 36497132, 2022).
emphysema (5 papers, 2013 to 2021). "Adgrf5-deficient (Adgrf5−/−) mice exhibit an accumulation of foamy alveolar macrophages in the alveoli as well as emphysema-like signs including alveolar enlargement." (PMID 30654796, 2019). "We previously showed that in addition to abnormal surfactant accumulation, Adgrf5-deficient (Adgrf5−/−) mice exhibit emphysema-like signs, suggesting a possible role for ADGRF5 in immune regulation." (PMID 30654796, 2019). "Therefore, alveolar macrophages from Adgrf5−/− mice retain the ability to induce emphysema symptoms and airway inflammation." (PMID 30654796, 2019).
Insulin resistance (3 papers, 2021 to 2024). Increased resistance towards insulin, that is, diminished effectiveness of insulin in reducing blood glucose levels. "ADGRF5 was also found to be expressed in adipose tissue and may play a beneficial role in glucose tolerance and insulin resistance." (PMID 38898596, 2024).
asthma (2 papers, 2019 to 2024). "Type-2 inflammation is likely to promote the loss of function of ADGRF5 and GRP78 in a positive feedback manner, thus creating a vicious circle of chronic airway inflammation and making asthma refractory." (PMID 38395974, 2024). "Since neutrophilic inflammation is common during COPD, severe asthma, cystic fibrosis, and bronchiectasis, all of which involve airway mucus hypersecretion, infiltrating neutrophils, in addition to eosinophils, might contribute to the progression of airway inflammation in Adgrf5−/− mice." (PMID 30654796, 2019).
lung carcinoma (2 papers, 2021 to 2025). "For lung cancer, all manuscript-referenced genes were captured by either SHAP or LIME, with notable overlaps such as MYBL2, HYAL1, CLIC5, ADGRF5, and CLDN18." (PMID 40565055, 2025).
migraine (2 papers, 2024 to 2025). "ADGRF5 (a protein) was significantly associated with the risk of migraine (OR = 0.964, 95% CI: 0.946–0.982, p = 8.74 × 10−5) and suggestively associated with MWA." (PMID 40994718, 2025). "ADGRF5 was significantly associated with the risk of migraine (OR = 0.964, 95% CI: 0.946–0.982, p = 8.74 × 10−5)." (PMID 40994718, 2025). "ADGRF5 was significantly associated with the risk of any migraine (OR = 0.964, 95% CI = 0.946–0.982, p = 8.74 × 10−5) and suggestively associated with migraine with aura." (PMID 38898596, 2024). "Furthermore, we observed compelling evidence that ADGRF5 was linked to a decreased risk of overall migraine and suggestive evidence that it was associated with a decreased risk of migraine with aura." (PMID 38898596, 2024). "Additionally, ITIH4 (OR = 0.862, p = 4.69 × 10−5) and ADGRF5 (OR = 0.964, p = 8.74 × 10−5) were significantly associated with a decreased risk of any migraine." (PMID 38898596, 2024). "We identified three tier 1 proteins (LRP11, ITIH1, and ADGRF5), whose genes have not been previously identified as causal genes for migraine in genetic studies." (PMID 38898596, 2024). "Therefore, the safety of targeting ADGRF5 for migraine should be further investigated." (PMID 38898596, 2024).
pulmonary alveolar proteinosis (2 papers, 2013 to 2019). A rare lung disorder characterized by the filling of the pulmonary alveoli with proteinaceous material which stains positive with periodic acid-Schiff stain. "Adgrf5−/− mice show several key features of pulmonary alveolar proteinosis (PAP), such as the accumulation of pulmonary surfactant and foamy alveolar macrophages in the alveolar space." (PMID 30654796, 2019).
Acidosis (1 paper, 2019). Abnormal acid accumulation or depletion of base. "Our study showed for the first time that Adgrf5−/− mice exhibit characteristic features of airway inflammation, including mucous cell metaplasia, mucus hyperproduction, type 2 inflammation, subepithelial fibrosis, and respiratory acidosis." (PMID 30654796, 2019).
colitis (1 paper, 2026). Inflammation of the colon. "The adhesion G protein-coupled receptor F5 (ADGRF5) has been implicated in modulating immune responses in cancer; however, its role in inflammatory bowel diseases (IBDs), particularly colitis, remains largely unexplored." (PMID 41898510, 2026). "In this study, we aimed to design and characterize novel peptide agonists derived from the ADGRF5 Stachel sequence, as well as to evaluate their therapeutic potential in preclinical colitis models." (PMID 41898510, 2026). "Finally, using these novel ADGRF5 agonists, we demonstrated their potent anti-inflammatory effects in vivo, showing that ADGRF5 activation ameliorates experimental colitis, as evidenced by reduced macroscopic damage scores and improved colon architecture." (PMID 41898510, 2026).
colon adenocarcinoma (1 paper, 2022). "We found an increased expression of ADGRF5 in CRC patients with a mucinous type of colon adenocarcinoma compared to colon adenocarcinoma (p < 0.01)." (PMID 36497132, 2022). "In addition, we found an increased expression of ADGRF5 in patients with a mucinous type of colon adenocarcinoma compared to colon adenocarcinoma." (PMID 36497132, 2022).
dementia (1 paper, 2025). Loss of intellectual abilities interfering with an individual's social and occupational functions. "Considering the expression of NPB and ADGRF5 in the central nervous system, these findings suggest that autoantibodies targeting NPB or ADGRF5 may contribute to the pathogenesis of dementia." (PMID 40406128, 2025).
melanoma (1 paper, 2018). A malignant, usually aggressive tumor composed of atypical, neoplastic melanocytes. "ADGRG1 knockdown resulted in melanoma growth inhibition and regression, while knockdown of the other 2 aGPCRs reduced lung (ADGRF5) and/or bone metastasis (ADGRE5, ADGRF5)." (PMID 29468160, 2018).
polymicrogyria (1 paper, 2017). A developmental brain abnormality characterized by an excessive amount of small convolutions on the surface of the brain and cognitive dysfunction. "For example, dysfunction of ADGRG1/GPR56 causes polymicrogyria, ADGRF5/GPR116 controls pulmonary surfactant production, genetic lesions in many aGPCR loci are associated with a roster of cancer types and ADGRE2/EMR2 regulates mast cell degranulation." (PMID 28784204, 2017).
pulmonary fibrosis (1 paper, 2025). Chronic progressive interstitial lung disorder characterized by the replacement of the lung tissue by connective tissue, leading to progressive dyspnea, respiratory failure, or right heart failure. "Although there is insufficient evidence directly linking ADGRF5 to human pulmonary fibrosis, its roles in airway inflammation, fibrosis-related gene expression, and immune regulation suggest that ADGRF5 may serve as a potential therapeutic target or biomarker for fibrotic lung diseases." (PMID 41007698, 2025).
pyelonephritis (1 paper, 2022). An inflammatory process affecting the kidney. "Signaling via adenosine receptors, ADORA2A or ADORA2B, stimulates proton secretion by α‐ICs; thus adenosine production in pyelonephritis‐induced tissue injury may trigger dysregulated urine acidification leading to systemic alkalosis as is the case in GPR116 or ADGRF5‐deficient mice." (PMID 36151614, 2022).
renal oncocytoma (1 paper, 2024). "Expression of biomarkers MAPRE3, ADGRF5, and GPNMB differentiates renal oncocytoma from chromophobe RCC, and PIGR and SOSTDC1 distinguish papillary RCC from MTSCC." (PMID 38703764, 2024).
cancer (14 papers, 2017 to 2026). A tumor composed of atypical neoplastic, often pleomorphic cells that invade other tissues. "Other genes from this list are linked to various types of cancer (Pnck, Calu, Vav2, Kif3a, Adgrf5, N4bp2l2)." (PMID 32467583, 2020). "The investigators found that low levels of ADGRF5 in highly metastatic cancer cells inhibited cell migration and invasion in vitro, whereas ectopic ADGRF5 expression in low metastatic cells had the opposite effect." (PMID 39935605, 2025). "Adhesion G protein-coupled receptor F5 (ADGRF5) is involved inthe neoplastic transformation of some cancer types." (PMID 36497132, 2022). "Little is known about the possible mechanisms responsible for the induction of ADGRF5 expression in cancer." (PMID 36497132, 2022). "Accumulating evidence indicates that ADGRF5 is a crucial member of adhesion GPCRs that mediate numerous processes such as proliferation, apoptosis, and migration, as well as invasion in the progression of some cancer types." (PMID 36497132, 2022). "However, it has been suggested that ADGRF5 may be a potent regulator of cancer progression." (PMID 38898596, 2024). "ADGRF5, also called GPR116, is an adhesion G protein-coupled receptor, and an emerging role in cancers for this family of proteins is being investigated." (PMID 38703764, 2024). "Detailed in vitro and in vivo analyses further indicated that ADGRG1 is a prosurvival factor in cancer cells and promotes anchorage-independent growth whereas ADGRE5 and ADGRF5 regulate RhoA-dependent cell migration and invasion." (PMID 29468160, 2018). "A recent study analyzing cancer-specific splicing in more than 1,000 patients identified a non-canonical ADGRF5/GPR116 isoform with an altered C terminus representing an alternative spliced ADGRF5/GPR116 variant." (PMID 31363148, 2019).
tumor (11 papers, 2017 to 2025). "It was also shown that the loss of ADGRF5 increased the expression of MMP-8, a metalloprotease that leads to the secretion of CXCL8, resulting in increased infiltration of tumour associated neutrophils (TANs)." (PMID 39982274, 2025). "Significantly higher copy numbers of the ADGRF5 gene (p < 0.05) were found in CRC patients with nearby lymph nodes affected by tumor cells (N1/2) in relation to CRC patients, which were characterized by a lack of tumor cells in the nearby lymph nodes (N0)." (PMID 36497132, 2022). "Of note, ADGRF5 expression correlated with the levels of tumor-infiltrating immune cells in the colon of CRC patients." (PMID 36497132, 2022). "Analysis of ADGRF5 expression in CRC patients according to tumor-node-metastasis (TNM) staging system revealed higher expression of ADGRF5 when the extent of the tumors was classified as a T3 and T4 compared to the tumors described as a T1 and T2 (p < 0.01)." (PMID 36497132, 2022). "Additionally, our analyses document the link between ADGRF5 expression and the levels of tumor-infiltrating immune cells in the colon and rectum of patients with adenocarcinomas." (PMID 36497132, 2022). "More importantly, STEAP4 and ADGRF5 specifically expressed in subgroup 3 and 4 showed a significant overexpression of CXCR4 and SRGN, which were closely related to tumor metastasis or immunosuppression in TME." (PMID 37221625, 2023). "Furthermore, STEAP4+, ADGRF5 + and CXCR4+, and SRGNC + fibroblast subgroups were closely related to tumor progression, tumor metabolism, and immunosuppression, indicating their contributions in PCa metastasis." (PMID 37221625, 2023).
infection (3 papers, 2022 to 2025). The state of being infected such as from the introduction of a foreign agent such as serum, vaccine, antigenic substance or organism. "Additionally, genes related to cell adhesion such as ADGRF5, CAVIN2, FAT3, FILIP1, GSN, and TSPAN11 were downregulated in both the variants at 24hpi whereas CAV1, CAVIN1, GPC3, POSTN, SUSD2, and TSPAN7 were downregulated only after Delta variant infection at 24 hpi." (PMID 41200555, 2025). "Similarly, chemokines (e.g. CXCL1, CXCL2, and CXCL5) that play a pivotal role in neutrophil recruitment to sites of infection and injury were induced 2–3 orders of magnitude, whereas CXCL12/SDF‐1 and adhesion G‐protein coupled receptor F5 (ADGRF5, GPR116) expression was unaffected." (PMID 36151614, 2022).
adenocarcinoma (1 paper, 2022). A common cancer characterized by the presence of malignant glandular cells. "On the other hand, the level of B cells infiltration was negatively correlated (R = −0.12, p < 0.05) with the expression of ADGRF5 in the colon of patients with adenocarcinoma." (PMID 36497132, 2022). "The levels of dendritic cells (R = 0.61), macrophages (R = 0.56), neutrophils (R = 0.55), CD8+ (R = 0.32), and CD4+ (R = 0.31) T cells, as well as B cells (R = 0.10) infiltration, were positively correlated (p < 0.05) with the expression of ADGRF5 in the rectum of patients with adenocarcinoma." (PMID 36497132, 2022).
inflammation (1 paper, 2019). Aberrant reaction of the microcirculation characterized by movement of fluid and leukocytes from the blood into extravascular tissues. "We found that Adgrf5−/− mice exhibit abnormal histological and physiological features in the lungs, resembling those of airway inflammation, and investigated time-course expression profiles of genes/proteins related to this disorder." (PMID 30654796, 2019).
ADGRF5 also shares sentences with these, for which no sentence is quoted: pancreatic cancer (3 papers); diabetes (2); gastric cancer (2); glioblastoma (2); glioma (2); lung adenocarcinoma (2); prostate carcinoma (2); Sepsis (2); thrombotic microangiopathies (2); atherosclerosis (1); brain arteriovenous malformation (1); bronchiectasis (1); colon carcinoma (1); cystic fibrosis (1); eosinophilia (1); frontoparietal polymicrogyria (1); glomerulopathy (1); Hepatic steatosis (1); hepatocellular carcinoma (1); Hyperglycemia (1); Hyperinsulinemia (1); Impaired glucose tolerance (1); inflammatory bowel disease (1); kidney disease (1); kidney failure (1); liver diseases (1); lung diseases (1); lymph node metastasis (1); migraine with aura (1); ovarian carcinoma (1).
A further 5 diseases each share a sentence with ADGRF5 in 1 paper.